PLXNA2 (plexin A2)
Description:
Coreceptor for SEMA3A and SEMA6A. Necessary for signaling by SEMA6A and class 3 semaphorins and subsequent remodeling of the cytoskeleton. Plays a role in axon guidance, invasive growth and cell migration. Class 3 semaphorins bind to a complex composed of a neuropilin and a plexin. The plexin modulates the affinity of the complex for specific semaphorins, and its cytoplasmic domain is required for the activation of down-stream signaling events in the cytoplasm (By similarity).
Synonyms: KIAA0463; OCT; PLXN2; FLJ11751; FLJ30634
Tractability: Small molecule: a structure with a bound ligand is known. Antibody: its Gene Ontology location is reachable by antibodies, with high confidence; UniProt places it where antibodies can reach, with medium confidence; UniProt predicts a signal peptide or a membrane-spanning region. PROTAC: ubiquitination databases record sites on it; its protein half-life has been measured.
Gene: Protein-coding gene on chromosome 1 (208,022,242 to 208,244,850, reverse strand). Ensembl gene ENSG00000076356.
Subcellular location: Cell membrane
Pathways (Reactome):
Developmental Biology: CRMPs in Sema3A signaling; Other semaphorin interactions; SEMA3A-Plexin repulsion signaling by inhibiting Integrin adhesion; Sema3A PAK dependent Axon repulsion
Gene Ontology:
Molecular function: protein binding; semaphorin receptor activity; identical protein binding; transmembrane signaling receptor activity
Biological process: regulation of cell migration; semaphorin-plexin signaling pathway; synapse assembly; anatomical structure morphogenesis; animal organ development; limb bud formation; nervous system development; neural tube development; pharyngeal system development; somitogenesis; tube development
Cellular component: plasma membrane; semaphorin receptor complex
Genetic constraint (gnomAD): Loss-of-function variants: 82 observed, 187.6 expected, observed/expected ratio (o/e) 0.44, 90% interval 0.37 to 0.52. The upper end of that interval is the gene's LOEUF score, 0.52, which puts it in group 2 of 6, group 1 being the genes least tolerant of losing a copy. Missense variants: 1,968 observed, 2,579.8 expected, observed/expected ratio (o/e) 0.76, 90% interval 0.73 to 0.79. Synonymous variants: 985 observed, 1,069.7 expected, observed/expected ratio (o/e) 0.92, 90% interval 0.87 to 0.97.
Homologues: Orthologues: chimpanzee PLXNA2 (99% identical), macaque PLXNA2 (99% identical), rabbit PLXNA2 (98% identical), rat Plxna2 (97% identical), mouse Plxna2 (97% identical), guinea pig PLXNA2 (97% identical), pig PLXNA2 (89% identical), tropical clawed frog plxna2 (85% identical), zebrafish plxna2 (81% identical). Paralogues in human: PLXNA4 (67% identical), PLXNA1 (64% identical), PLXNA3 (59% identical), PLXNB1 (35% identical), PLXNB3 (33% identical), PLXND1 (32% identical), PLXNB2 (32% identical), PLXNC1 (22% identical).